Y_RNA (Y RNA )
Gene: Miscellaneous RNA gene on chromosome 1 (51,107,222 to 51,107,331, forward strand). Ensembl gene ENSG00000200262.
Homologues: Orthologues: chimpanzee Y_RNA (99% identical). Paralogues in human: Y_RNA (82% identical), Y_RNA (81% identical), RNY1P5 (80% identical), RNY1 (79% identical), Y_RNA (79% identical), Y_RNA (78% identical), Y_RNA (77% identical), RNY1P11 (76% identical), RNY1P14 (76% identical), Y_RNA (76% identical), Y_RNA (75% identical), RNY1P16 (75% identical), and 91 more.